ADAMTS16 (ADAM metallopeptidase with thrombospondin type 1 motif 16)
Synonyms: ADAMTS16s
Tractability: Antibody: UniProt places it where antibodies can reach, with medium confidence; UniProt predicts a signal peptide or a membrane-spanning region; its Gene Ontology location is reachable by antibodies, with medium confidence.
Gene: Protein-coding gene on chromosome 5 (5,140,329 to 5,320,304, forward strand). Ensembl gene ENSG00000145536.
Subcellular location: Secreted, extracellular space, extracellular matrix
Subcellular location (Human Protein Atlas): Vesicles; Predicted to be secreted
Pathways (Reactome):
Disease: Defective B3GALTL causes PpS
Extracellular matrix organization: Degradation of the extracellular matrix
Metabolism of proteins: O-glycosylation of TSR domain-containing proteins
Gene Ontology:
Molecular function: metalloendopeptidase activity; metallopeptidase activity
Biological process: extracellular matrix organization; proteolysis; male gamete generation; regulation of cilium assembly; regulation of systemic arterial blood pressure
Cellular component: extracellular matrix
Genetic constraint (gnomAD): Loss-of-function variants: 89 observed, 133.75 expected, observed/expected ratio (o/e) 0.67, 90% interval 0.56 to 0.79. The upper end of that interval is the gene's LOEUF score, 0.79, which puts it in group 3 of 6, group 1 being the genes least tolerant of losing a copy. Missense variants: 1,559 observed, 1,537.5 expected, observed/expected ratio (o/e) 1.01, 90% interval 0.97 to 1.06. Synonymous variants: 648 observed, 585.14 expected, observed/expected ratio (o/e) 1.11, 90% interval 1.04 to 1.18.
Homologues: Orthologues: chimpanzee ADAMTS16 (99% identical), macaque ADAMTS16 (96% identical), dog ADAMTS16 (85% identical), mouse Adamts16 (83% identical), rabbit ADAMTS16 (83% identical), pig ADAMTS16 (82% identical), rat Adamts16 (81% identical), tropical clawed frog adamts16 (66% identical), guinea pig ADAMTS16 (61% identical), zebrafish adamts16 (59% identical). Paralogues in human: ADAMTS18 (55% identical), ADAMTS6 (35% identical), ADAMTS7 (34% identical), ADAMTS12 (34% identical), ADAMTS10 (33% identical), ADAMTS9 (31% identical), ADAMTS20 (29% identical), ADAMTS2 (28% identical), ADAMTS3 (27% identical), ADAMTS19 (27% identical), ADAMTS14 (27% identical), ADAMTS17 (27% identical), and 13 more.
Diseases named in the same sentence as ADAMTS16 in open-access papers:
ADAMTS16 is named in the same sentence as 45 diseases in open-access papers, as found by Europe PMC text mining. Sharing a sentence is not in itself a finding about the gene and the disease. The quoted sentences say what the papers report.
chondrosarcoma (5 papers, 2017 to 2025). A malignant cartilaginous matrix-producing mesenchymal neoplasm arising from the bone and soft tissue. "The steady increase in the expression of ADAMTS16 will cause the inhibition of cell proliferation, migration, and adhesion, and a decrease in the expression of matrix metalloproteinase-13 (MMP13) in chondrosarcoma cells." (PMID 34389038, 2021). "On the other hand, a study reported that ADAMTS16 overexpression resulted in significantly reduced proliferation in chondrosarcoma cells." (PMID 29179445, 2017). "Although overexpression of ADAMTS-16 led to decreased MMP-13 expression in chondrosarcoma cells, the role of ADAMTS-16 in OA progression and especially in the meniscal degradation is still unknown." (PMID 40724902, 2025).
Hypertension (5 papers, 2011 to 2020). The presence of chronic increased pressure in the systemic arterial system. "ADAMTS-16 is implicated in a number of pathological conditions, including hypertension, cancer and osteoarthritis." (PMID 31748609, 2019). "Although studies have demonstrated an association between ADAMTS16 and disease such as hypertension, osteoarthritis, premature ovarian failure and Dupuytren’s disease, less is known about the function of the gene than about other members of the ADAMTS family." (PMID 29179445, 2017). "Genome-wide association studies have identified ADAMTS16 as a candidate locus involved in inherited hypertension, and this candidacy is supported by targeted disruption of Adamts16 in a rat model." (PMID 26025392, 2015). "ADAMTS16 was indeed significantly associated with human hypertension in two independent cohorts." (PMID 22379396, 2011). "Although not yet detected in human genetic disorders, inactivation of the Adamts16 gene in rodents has been shown to lead to hypertension, cryptorchidism and male infertility, and aberrant renal development." (PMID 26025392, 2015).
colorectal cancer (3 papers, 2018 to 2025). A primary or metastatic malignant neoplasm that affects the colon or rectum. "The change reduced the level of the ADAMTS16 gene transcript, thus increasing the risk of colorectal cancer." (PMID 39940703, 2025). "Overexpression of ADAMTS16 in HT29 colorectal cancer cells significantly reduced cell proliferation." (PMID 30081852, 2018). "Functional in vitro studies using the colorectal carcinoma cell line HT29 revealed that ADAMTS16 expression restrained tumor cell proliferation." (PMID 30081852, 2018). "Finally, overexpression of ADAMTS16 in HT29 colorectal cancer cells dramatically decreased cell growth." (PMID 30081852, 2018). "In colorectal cancer (CRC), ADAMTS16 was hypermethylated and high expression of ADAMTS16 restrained cancer cell proliferation." (PMID 36232317, 2022).
lung carcinoma (3 papers, 2023 to 2025). "Higher levels of ADAMTS1 (OR: 1.28, 95% CI: 1.14–1.41) and ADAMTS16 (OR: 1.1, 95% CI: 1.01--1.19) were genetically predicted to be associated with lung cancer." (PMID 39551781, 2024). "Analysis of transcriptomic data from larger lung cancer patient cohorts, however, revealed increased tumour expression of genes encoding both peroxidasin and ADAMTS16, and this was separately linked to poorer survival of lung adenocarcinoma and squamous cell carcinoma patients, respectively." (PMID 37397358, 2023). "ADAMTS16 DNA methylation has been shown to be dysregulated in several epithelial cancers, including lung cancer, suggesting that regulation of ADAMTS16 protein expression in tumour-associated ECM, and its potential as a protein biomarker in NSCLC, warrant investigation." (PMID 37397358, 2023). "Both ADAMTS1 and ADAMTS16, promote lung cancer metastasis in animal models: ADAMTS1 accelerates spontaneous pulmonary metastasis of Lewis lung carcinoma in C57BL/6 mice, while ADAMTS16 enhances pulmonary metastasis of A549 cells following tail vein injection in nude mice." (PMID 41465277, 2025).
osteoarthritis (3 papers, 2017 to 2021). A noninflammatory degenerative joint disease occurring chiefly in older persons, characterized by degeneration of the articular cartilage, hypertrophy of bone at the margins and changes in the synovial membrane. "Current studies have shown that the expression of ADAMTS16 is increased in cartilage and synovium from osteoarthritis patients compared with normal controls." (PMID 34389038, 2021).
coloboma (2 papers, 2020 to 2021). An abnormality in which a part of a structure in one or both eyes is missing. "The low prevalence of the coloboma phenotype in our medaka model can be explained as a result of both, the mosaic organism generated upon injection of the CRISPR/Cas9 system and the non–cell autonomous effect of the secreted ADAMTS16 protease." (PMID 33975020, 2021).
esophageal cancer (2 papers, 2015 to 2017). A primary or metastatic malignant neoplasm involving the esophagus. "A previous study reported that deletion of ADAMTS16 in esophageal cancer cells inhibited invasion." (PMID 29179445, 2017). "ADAM17 and esophageal cancer studies were rarely reported, Sakamoto, etc. used the RT-PCR and western blot analysis protein electrophoresis methods, they detected the elevated ADAMTS16 protein expression in esophageal tissues." (PMID 25351873, 2015). "In the medium TE5 esophageal cancer cell lines, ADAMTS16 protein levels were detected." (PMID 25351873, 2015). "By blocking the ADAMTS16, the growth and invasion of TE5 esophageal cancer cell can be inhibited." (PMID 25351873, 2015).
esophageal squamous cell carcinoma (2 papers, 2017 to 2022). Esophageal squamous cell carcinoma (ESCC) is a type of esophageal carcinoma (EC) that can affect any part of the esophagus, but is usually located in the upper or middle third. "As a member of the ADAMTS proteins family, ADAMTS16 was first revealed in the oncogene esophageal squamous cell carcinoma." (PMID 36232317, 2022). "ADAMTS16 protein level of stable cell lines was detected in both the cell lysate and conditioned medium as previously reported in esophageal squamous cell carcinoma." (PMID 29179445, 2017). "On the contrary, knockdown ADAMTS16 expression in esophageal squamous cell carcinoma could inhibit cell invasion and proliferation." (PMID 36232317, 2022).
gastric cancer (2 papers, 2022 to 2025). A primary or metastatic malignant neoplasm involving the stomach. "For example, ADAMTS16 has been shown to promote gastric cancer growth." (PMID 41146049, 2025). "In recent years, the degradation of ECM has also been shown to promote tumor development, but the role of ADAMTS16 in gastric cancer remains unclear." (PMID 36232317, 2022). "In this study, the role of ADAMTS16 in gastric cancer was investigated." (PMID 36232317, 2022). "In addition, the prognostic role of ADAMTS16 in gastric cancer was also confirmed." (PMID 36232317, 2022). "In this study, a series of functional experiments have confirmed the regulation of ADAMTS16/NF-κB/IFI27 signaling axis in the development of gastric cancer, suggesting that ADAMTS16 can be regarded as a potential target for the treatment of gastric cancer." (PMID 36232317, 2022). "Therefore, it is urgent for us to further study ADAMTS16 to promote the occurrence and development of GC, expecting to play a certain guiding role in the strategy of gastric cancer treatment." (PMID 36232317, 2022).
heart failure (2 papers, 2022 to 2023). Inability of the heart to pump blood at an adequate rate to meet tissue metabolic requirements. "It was shown that the overexpression of ADAMTS16 promoted cardiac fibrosis, cardiac hypertrophy, and heart failure by facilitating cardiac fibroblast activation." (PMID 37160311, 2023). "In a mice model for heart failure, ADAMTS16 is upregulated, its expression correlating with collagen expression." (PMID 36190948, 2022).
infertile (2 papers, 2014 to 2023). "Male Adamts2-KO and Adamts16-KO mice are infertile and are associated with a marked decrease in testicular sperm and cryptorchidism, respectively." (PMID 37656189, 2023). "Infertility was associated with the absence of Adamts16 transcripts in the testis, significantly diminished size of the testis, an age-dependent attrition of the seminiferous tubule and lack of spermatogenesis." (PMID 24983376, 2014).
Inguinal hernia (2 papers, 2022). Protrusion of the contents of the abdominal cavity through the inguinal canal. "Variants in ADAMTS16 have been associated with urinary incontinence, a manifestation of pelvic floor dysfunction, which have been shown independently to lead to a higher prevalence of hiatus and inguinal hernia." (PMID 36584111, 2022). "Pathway analyses identify several genes with a strong link to collagen and/or elastin (ADAMTS6, ADAMTS16, ADAMTSL3, LOX, ELN) in the vicinity of associated loci for inguinal hernia, which substantiates an essential role of connective tissue morphology." (PMID 35680855, 2022).
lung adenocarcinoma (2 papers, 2023 to 2024). A carcinoma that arises from the lung and is characterized by the presence of malignant glandular epithelial cells. "These proteins were up-regulated in lung tumour samples, and high PXDN and ADAMTS16 gene expression was associated with shorter survival of lung adenocarcinoma and squamous cell carcinoma patients, respectively." (PMID 37397358, 2023).
myocardial infarction (2 papers, 2025). Gross necrosis of the myocardium, as a result of interruption of the blood supply to the area, as in coronary thrombosis. "These anti-fibrotic properties also were observed in a rat myocardial infarction model where miR-29b-3 targeted ADAM with thrombospondin motifs 16 (ADAMTS16), a promoter of cardiac myofibroblasts that regulates angiogenic ventricular remodeling." (PMID 40676634, 2025).
ovarian carcinoma (2 papers, 2017 to 2018). A malignant neoplasm originating from the surface ovarian epithelium. "Among the ADAMTS mutations, ADAMTS-16 is the most commonly affected gene in ovarian cancer and exogenously expressed." (PMID 29393911, 2018). "Orthotopic xenograft experiments from the same group showed that mice injected with ovarian cancer cells that exogenously expressed ADAMTS-16 mutations had a better response to cisplatin treatment." (PMID 29393911, 2018). "To determine the role of these mutations in ovarian cancer cells, we established ovarian cancer cell lines that stably expressed empty vector (EV) or WT or each of the six ADAMTS16 missense mutants." (PMID 29179445, 2017). "We also used a well-characterized in vivo mouse model to evaluate the response of ovarian cancer cells with ADAMTS16 mutations to platinum-based therapy." (PMID 29179445, 2017). "Orthotopic xenograft experiments showed that mice injected with ovarian cancer cells that exogenously expressed ADAMTS16 mutations had a better response to cisplatin treatment." (PMID 29179445, 2017). "In summary, our investigations revealed that exogenously expressed ADAMTS16 missense mutations lead to cellular changes that enhance cisplatin sensitivity or inhibit cell growth and suppress tumor invasion and migration in platinum-resistant ovarian cancer." (PMID 29179445, 2017). "To determine whether the presence of ADAMTS16 mutation in ovarian cancer cells also changes the phenotype, we performed a migration and invasion assay." (PMID 29179445, 2017). "We evaluated phenotypes of ovarian cancer cells with ADAMTS16 mutations." (PMID 29179445, 2017). "Thus, these functional studies provide evidence that mutations of ADAMTS16 actively contribute to therapeutic response in ovarian cancer." (PMID 29179445, 2017). "In this study, we hypothesized that ADAMTS16 mutations sensitize ovarian cancer cells to platinum-based chemotherapy." (PMID 29179445, 2017). "Among the ADAMTS mutations, ADAMTS16 is the most commonly affected gene in ovarian cancer." (PMID 29179445, 2017). "ADAMTS16 is a potential therapeutic target in patients with platinum-resistant ovarian cancer." (PMID 29179445, 2017). "With no prior knowledge of the biological function of ADAMTS16 mutations in ovarian cancer cells, we first generated six ADAMTS16 mutants on the basis of the missense mutations detected on this gene: C274R, F660I, S787Y, A1155V, S1170L and K1206." (PMID 29179445, 2017). "In our previous study, we demonstrated that mutations of eight members of the ADAMTS family (including ADAMTS16 gene) were significantly associated with chemotherapy sensitivity and longer survival in patients with ovarian cancer, independent of BRCA1 or BRCA2 mutations." (PMID 29179445, 2017). "To test this hypothesis, we performed in vitro studies to compare the drug response in ovarian cancer cells with and without one of the six ADAMTS16 missense mutations." (PMID 29179445, 2017).
colorectal adenocarcinoma (1 paper, 2018). The most common type of colorectal carcinoma. "The human colorectal adenocarcinoma cell line HT29 was used for the analysis of ADAMTS16 function." (PMID 30081852, 2018).
diabetes (1 paper, 2025). "ADAMTS16 has not been associated with any glycaemic traits in GWASs; however, a SNP in ADAMTS9 has been shown to be associated with increased type 2 diabetes risk, suggesting that ADAMTS gene family members contribute to diabetes pathophysiology." (PMID 40025146, 2025).
gastric tumors (1 paper, 2022). "In this study, clinicopathological analysis revealed that abnormal overexpression of ADAMTS16 was associated with a poor prognosis in human gastric tumors." (PMID 36232317, 2022).
glioblastoma (1 paper, 2025). The most malignant astrocytic tumor (WHO grade IV). "For instance, interactions between LTF and ADAMTS16 in glioblastoma indicate a possible role in epithelial to mesenchymal transition." (PMID 41020875, 2025).
Insulin resistance (1 paper, 2025). Increased resistance towards insulin, that is, diminished effectiveness of insulin in reducing blood glucose levels. "Fine mapping showed that lead SNPs at both B4GALT6 (rs6506934; pp=0.89) and ADAMTS16 (rs74806991; pp=0.99) are candidate causal variants associated with insulin resistance." (PMID 40025146, 2025).
lymph node metastasis (1 paper, 2022). "High ADAMTS16 protein expression was significantly associated with invasion depth (p = 0.046), lymph node metastasis (p = 0.025), vascular invasion (p = 0.032), and pTNM stage (p = 0.006)." (PMID 36232317, 2022). "Meanwhile, ADAMTS16 was significantly associated with the pathological characteristics including lymph node metastasis, local invasion, and vascular invasion." (PMID 36232317, 2022). "In GC, ADAMTS16 mRNA expression was significantly correlated with age (p = 0.004), invasion depth (p = 0.013), lymph node metastasis (p = 0.042), distance metastasis stage (p = 0.004), and TNM stage (p = 0.011)." (PMID 36232317, 2022).
psoriasis (1 paper, 2018). An autoimmune condition characterized by red, well-delineated plaques with silvery scales that are usually on the extensor surfaces and scalp. "Top up-regulated DEGs in CP vs C include previously identified psoriasis-associated genes such as IL36A/G, SPRR2A/B/F, SERPINB4, S100A7A, S100A9, and IL17F while top down-regulated DEGs include SERTM1, IL6, and ADAMTS16." (PMID 30054515, 2018).
renal carcinoma (1 paper, 2024). A carcinoma arising from the epithelium of the renal parenchyma or the renal pelvis. "ADAMTS16 was also associated with sensitivity to platinum-based chemotherapy in ovarian cancer cells and prognosis in renal cancer." (PMID 39551781, 2024). "Previous studies reported that ADAMTS16 facilitates gastric carcinogenesis and predicts unfavorable outcomes in renal cancer patients." (PMID 39551781, 2024).
squamous cell carcinoma (1 paper, 2023). A carcinoma arising from squamous epithelial cells. "In contrast, there was no statistical association of expression of PXDN with survival of squamous cell carcinoma patients, whereas higher expression of ADAMTS16 was significantly associated with shorter survival of squamous cell carcinoma patients (HR = 1.72; 95% CI, 1.18–2.50; P = 0.0043)." (PMID 37397358, 2023). "Median survival of squamous cell carcinoma patients was 74.1 months for the low ADAMTS16 expression subgroup and 33.4 months for the high ADAMTS16 expression subgroup." (PMID 37397358, 2023).
type 2 diabetes (1 paper, 2025). "Both ADAMTS16 and B4GALT6 are implicated in the development of type 2 diabetes." (PMID 40025146, 2025).
urgency urinary incontinence (1 paper, 2022). "One of the ADAMTS members, ADAMTS16, was identified as genome wide suggestive in a genome-wide association study (GWAS) on urgency urinary incontinence (UUI), indicating the involvement of ADAMTS16 in this pelvic floor dysfunction." (PMID 34973089, 2022).